MEN1 (menin 1)
Diseases named in the same sentence as MEN1 in open-access papers (continued):
Sharing a sentence is not in itself a finding about the gene and the disease.
parathyroid tumors (continued). "We have demonstrated that the expression level of WT1 is significantly decreased in MEN1-parathyroid tumors compared to normal parathyroid tissues." (PMID 26871472, 2016). "Sox family members were hypermethylated in all human MEN1-parathyroid tumors as compared to normal human parathyroid tissue (P value < 0.0001) and showed significant decrease in their mRNA expression (P value < 0.001)." (PMID 26871472, 2016). "Using a novel genome-wide methylation analysis, we studied tissues from MEN1-parathyroid tumors, Men1 knockout (KO) mice, and Men1 null mouse embryonic fibroblast (MEF) cell lines." (PMID 26871472, 2016). "The Sox gene family in particular was found to have significant hypermethylation in MEN1-parathyroid tumors compared to normal parathyroid tissue." (PMID 26871472, 2016). "MEN1 patients also develop multiple parathyroid tumors, and subtotal parathyroidectomy has resulted in persistent or recurrent hypercalcaemia within 10 years in 20–60% of MEN1 patients, as opposed to ∼4% in non-MEN1 patients." (PMID 23933118, 2014). "Biallelic MEN1 loss was noted in a parathyroid tumor from patient DK-2127, but neither of the 2 variants were noted in the patient’s germline DNA on WES or Sanger sequencing or in the germline DNA of the patient’s sister with genotype-negative MEN1." (PMID 39946193, 2025). "Recent research has also demonstrated that tumorigenesis in MEN1, including development of parathyroid tumors, may be influenced by epigenetic factors." (PMID 39519139, 2024). "The authors describe nuclear Menin loss in parathyroid tumors in 16/16 (100.0%) MEN1 patients of their single-center cohort, with MEN4 not taken into account." (PMID 38244045, 2024). "A study by Shen and colleagues identified 23 Hox genes whose expression was dysregulated in MEN1-associated parathyroid tumors compared to sporadic parathyroid tumors and non-malignant parathyroid tissue." (PMID 39336822, 2024). "mRNA analyses have demonstrated that Menin expression is downregulated in MEN1 parathyroid tumors." (PMID 38244045, 2024). "The patient was found to have a common germline MEN1 single nucleotide polymorphism (thus she did not have MEN1), and the breast and parathyroid tumors showed LOH at the MEN1 locus." (PMID 36325452, 2022). "The expression of MEN1 in subgroups of parathyroid tumors is still worthy of further analysis." (PMID 35879975, 2022). "Molecular alterations associated with parathyroid tumors include genomic aberrations in cell division cycle 7 (CDC7), cyclin D1 (CCND1), cyclin-dependent kinase inhibitor (CDKI), and multiple endocrine neoplasia type 1 (MEN1)." (PMID 33778063, 2021). "However, it is unclear how altered miR-199b-5p expression occurs within the context of dysregulated MEN1 in parathyroid tumors." (PMID 30104706, 2018). "Is there a hyperplastic precursor to the neoplastic parathyroid tumor in MEN1?" (PMID 30065698, 2018). "Four miRNAs, including miR-365, miR-125a-3p, miR-574-5p, and miR-1246, were significantly downregulated in sporadic parathyroid tumors, whereas miR-142-3p, let-7i, miR-125a-5p, miR-199b-5p, and miR-1274b_v16.0 were significantly upregulated; miR-193b was downregulated in MEN1 parathyroid tumors." (PMID 30104706, 2018). "Negative mutation testing is most prevalent in the clinical MEN1 phenotype comprising a combination of tumors of the parathyroids and pituitary gland." (PMID 30254610, 2018). "Knowledge about a hyperplastic precursor stage to parathyroid tumors in MEN1 could assist in planning interventions before a less responsive neoplastic mono- or oligo-clonal stage." (PMID 30065698, 2018). "MEN1, which is also referred as Wermer syndrome, is clinically characterized by the classical triad of tumors of the parathyroid glands, the pancreatic islet cells, and the anterior pituitary and it is inherited in an autosomal dominant manner with high penetrance." (PMID 28670351, 2017).
parathyroid tumors (continued). "MEN1 germline mutations have been reported in patients with hereditary and sporadic MEN1, and in FIHP and somatic MEN1 mutations are detected in approximately 20% of sporadic parathyroid tumors." (PMID 28881068, 2017). "We demonstrated a genome-wide increase in DNA methylation in MEN1-parathyroid tumors." (PMID 26871472, 2016). "Interestingly, specific deregulation of a subset of 23 Hox genes has been reported in parathyroid tumors from patients with MEN1." (PMID 23933118, 2014). "Notably, hyperfunctioning parathyroid tumors could also be incidentally discovered in patients with MEN1 undergoing somatostatin receptor PET/CT with [68Ga]-DOTA-peptides, a PET imaging technique employed to localize different types of endocrine tumors." (PMID 39795539, 2024). "Therefore, YAP1 and MEN1 mutually and differently regulated their expression levels, suggesting that genetic and epigenetic aberrations occurring in parathyroid tumors may determine the degree of activity of the two genes and their target genes." (PMID 33670622, 2021). "Thus, three miRNAs involved in the development of parathyroid tumors in MEN1 patients were identified, which could be used as possible diagnostic and prognostic biomarkers of this pathology." (PMID 34638805, 2021). "Patients with MEN1 (a heterozygous germline mutation in the MEN1 gene inherited in an autosomal-dominant fashion) have a 40%–80% chance of developing a PNET during their lifetime, making it the second-most-frequently expressed clinical manifestation of the syndrome next to parathyroid neoplasms." (PMID 33537001, 2020). "Therefore, the presence of constitutively mutated MEN1 alleles is not sufficient to explain the different tumor profiles between sporadic and hereditary parathyroid tumors." (PMID 30104706, 2018). "Notably, the majority of the dysregulated Hox genes were upregulated in MEN1-associated parathyroid tumors relative to non-malignant parathyroid tissue; however, the functional significance of these changes in Hox gene expression in the parathyroid remains unexplored." (PMID 39336822, 2024). "Parathyroid tumor-derived PHPT has been reported in up to 80–90% of patients with MEN4, presenting at a later age and with a milder clinical phenotype compared to MEN1, and with a female predominance." (PMID 34681865, 2021). "Why are some MEN1 lesions almost always benign (e.g., MEN 1 parathyroid tumors), whereas homozygous MEN1 inactivation is frequently found in malignant tumors of the endocrine pancreas?" (PMID 32884006, 2020). "Since PHPT has a high penetrance in adolescents with MEN1, it would be of some interest to know how early parathyroid tumors and PHPT begin in MEN1." (PMID 30065698, 2018). "What is the typical age of onset of parathyroid tumors and PHPT in MEN1? is there ever an onset in utero in MEN1?" (PMID 30065698, 2018). "MEN1 accounts for approximately 70% hereditary PHPT and parathyroid tumors occur in nearly 95% of MEN1 patients." (PMID 27846313, 2016). "Towards these ends, we have quantified promoter methylation of APC, RASSF1A, p16INK4A, RAR-β and LINE-1 repeats in a series of parathyroid tumours characterized for HRPT2 and MEN1 genotypes." (PMID 20208994, 2010). "HPT-JT is associated with a higher prevalence of PC, unlike MEN1 and MEN2 where parathyroid tumors generally are benign." (PMID 40115416, 2025). "Given the identification of the MEN1, RET, and CDC73 gene aberrancies as main responsible for the development of familial PHPT, numerous studies followed in which the involvement of these genes were assessed in sporadic parathyroid tumors." (PMID 33269427, 2021). "We have examined the methylation status of the secreted Wnt antagonists (sFRP, DKKs and WIF1) and observed no methylation changes in MEN1-parathyroid tumors compared to normal parathyroid tissues." (PMID 26871472, 2016).
parathyroid tumors (continued). "Quantitative RT-PCR analysis of the 39 HOX genes by an earlier study showed upregulation of 23 HOX genes among familial MEN1 parathyroid tumors with biallelic MEN1 loss, and downregulation of 5 HOX genes among sporadic parathyroid tumors without MEN1 loss." (PMID 22666422, 2012). "The sample collection consisted of 55 parathyroid tumours with known HRPT2 and/or MEN1 genotypes." (PMID 20208994, 2010). "Unlike HPT‐JT, many MEN1 patients with parathyroid tumors have multiglandular disease." (PMID 28881068, 2017).
pituitary tumor (59 papers, 1999 to 2026). A benign or malignant neoplasm affecting the pituitary gland. "The diagnostic criteria are the presence of two or more primary MEN1-related endocrine tumors such as parathyroid, pancreatic, or pituitary tumors." (PMID 40144450, 2025). "The aim of this study was to preliminarily verify the existence of differences in the genomes of MEN1 patients, that would associate with pituitary tumors or adrenocortical tumors." (PMID 38256138, 2024). "The management of pituitary tumors in patients with a confirmed MEN1 gene mutation follows standard treatment protocols." (PMID 39201946, 2024). "Pituitary tumors associated with MEN1 mutations tend to be larger, more aggressive, and resistant to conventional therapies." (PMID 39201946, 2024). "Somatic mutation of the MEN1 gene in sporadic pituitary tumors appears to be rare, including in those patients with sporadic CD." (PMID 37409236, 2023). "Thirty-three percent of familial probands with the co-occurrence of PHPT and pituitary tumors, but any proband with S-MEN1 with the same phenotype carried MEN1 mutations." (PMID 29036195, 2017). "The rate of association between PHPT and pituitary tumors was significantly lower (P<0.0001) in MEN1-positive than in MEN1-negative probands." (PMID 29036195, 2017). "To date, homologous deletions of 10 different genes, which are Men1, Cdkn1b, Prkar1a, Rb, Cdkn2b (encoding p19), Drd2, Cdkn2c (encoding p18), Aip, Prl and Prlr, have been reported to yield mouse knockout models for pituitary tumours." (PMID 26320859, 2016). "The aim of the present study was to analyze the MEN1 and gsα gene mutations in a Chinese patient with growth hormone-producing pituitary tumors causing acromegaly, papillary thyroid carcinoma and subcutaneous fibroma." (PMID 25663877, 2015). "Our study would support and extend very recent reports of a limited role for mutations in the MEN1 gene in sporadic pituitary tumours." (PMID 10389976, 1999). "In addition to individuals with pancreatic tumors, those with MEN1 are also at risk for pituitary tumors, parathyroid hyperplasia, and dermatologic manifestations." (PMID 41199767, 2025). "MEN1 mutations are most often associated with pancreatic, parathyroid, and pituitary tumors." (PMID 36428741, 2022). "Gigantism associated with MEN1 mutation occurs in approximately 1% of cases, this could be due to a pituitary tumour or, rarely, due to a GHRH-secreting pancreas tumour." (PMID 33805450, 2021). "Pituitary tumors associated with MEN1 occur mostly in the fourth decade of life." (PMID 33807230, 2021). "The functional significance of such changes in miRNA expression in endocrine tumourigenesis, especially in relation to MEN1-associated pituitary tumours remains unknown." (PMID 30389902, 2018). "The observation of increased cyclin D1 protein expression in association with down regulation of miR-15a and miR-16-1 in pituitary tumours from Men1+/− mice, suggests that cyclin D1 is a putative target of miR-15a and miR-16-1 in these Men1-associated pituitary tumours." (PMID 30389902, 2018). "The reason for these differences in pituitary-tumor formation is unclear but it might be related to the types of Men1 mutations (different exons were targeted) and/or differences in genetic background." (PMID 25136513, 2014). "However, pituitary tumours may represent the first disease manifestation, and considering the possibility of de novo mutations, screening for MEN1 should be considered in patients with childhood-onset pituitary macroadenomas (especially prolactinomas)." (PMID 33543431, 2021). "Due to the diagnosis of MEN1, screening for pituitary tumor was performed with biochemical evidence of acromegaly." (PMID 42007244, 2026). "Pituitary tumors in MEN1 cases show diverse hormonal activity: 60% secrete prolactin, around 25% secrete growth hormone, and 5% secrete corticotropin." (PMID 41155355, 2025).
pituitary tumor (continued). "While MEN1-associated tumors most commonly include parathyroid, pancreatic, and pituitary neoplasms, approximately 25% of all TNETs have been reported to occur in the setting of MEN1." (PMID 40563625, 2025). "Overall, pituitary tumors are represented by macroadenomas in 65–85% of MEN1 patients, the proportion being higher than that found in sporadic PitNETs." (PMID 39194755, 2024). "On the other hand, pituitary involvement affects 30–40% of MEN1 patients, and a significant proportion of all pituitary tumors (5% to 25%) are due to GH-secreting tumors." (PMID 39194755, 2024). "Our study is the first to address the different outcomes of MEN1 in means of pituitary tumor and adrenocortical tumor development based on genome-wide searching, without being restricted by previous knowledge-based choices of the analyzed genes." (PMID 38256138, 2024). "Another cause of ACTH-dependent CS in MEN1 patients, apart from ACTH-secreting pituitary tumors causing CD, are extrapituitary neuroendocrine tumors that secrete ACTH ectopically." (PMID 37409236, 2023). "Pituitary tumors are present in about 40% of MEN1 patients, and up to 10% of such tumors secrete ACTH that can result in Cushing’s disease." (PMID 37409236, 2023). "Up to 5% of all pituitary tumors are hereditary e.g. due to MEN1 or aryl hydrocarbon receptor-interacting protein (AIP) genes mutations." (PMID 36843582, 2023). "It has been suggested that MEN1 gene replacement, by the use of adenoviral vectors, would decrease pituitary tumour proliferation." (PMID 33805450, 2021). "The AIPmut nonfunctioning microadenomas we have identified in our study are somewhat similar to the screening-detected MEN1-related pituitary tumors described elsewhere." (PMID 31996917, 2020). "In 65–85% of MEN1 patients, pituitary tumors are represented by macroadenomas, a proportion that exceeds that recorded in sporadic tumors." (PMID 33312161, 2020). "Pituitary tumours were observed in the Men1+/- mice at necropsy, from the age of 13 months in the 129S6/SvEv strain and from 15 months of age in the C57BL/6 strain." (PMID 32348957, 2020). "We have therefore investigated the expression of miR-15a, miR-16-1 and let-7a in pituitary tumours that developed after 12 months of age in female mice with heterozygous knockout of the Men1 gene (Men1+/− mice)." (PMID 30389902, 2018). "The miRNAs miR-15a, miR-16-1 and let-7a were significantly downregulated in pituitary tumours (by 2.3-fold, P < 0.05; 2.1-fold P < 0.01 and 1.6-fold P < 0.05, respectively) of Men1+/− mice, compared to normal WT pituitaries." (PMID 30389902, 2018). "Mean age at diagnosis of pituitary tumours was 33.0 + 14.3 (range 7–69 years), while mean age of MEN1 diagnosis, for these patients, was 31.5 + 14.0 (range 7–57 years)." (PMID 30428914, 2018). "Regarding pituitary tumours, our patients showed a higher prevalence of PRLoma (over 41%) with respect to data reported in the MEN1 International guideline (20%), in the DMSG database (16%) and in the GTE cohort (30%)." (PMID 30428914, 2018). "In conclusion, we demonstrate that miR-15a and miR-16-1 are both downregulated in pituitary tumours of Men1+/− mice and that this decrease in expression correlates with an increase in cyclin D1 expression." (PMID 30389902, 2018). "This revealed a significant increase in CCND1 mRNA levels in Men1+/− pituitary tumours (n = 5), when compared to normal pituitaries (n = 5) from WT mice (2.6-fold, P < 0.0005)." (PMID 30389902, 2018). "Eighteen were index cases [mean age of pituitary tumour discovery 30.6+ 12.6 (range 12–55 years)] and 7 relatives of a MEN1 proband [mean age of pituitary tumour discovery 18.1+ 5.8 (range 12–30 years)]." (PMID 30428914, 2018). "A comparison between the clinical characteristics of F and S-MEN1 showed a higher prevalence of a single parathyroid disease and pituitary tumors in sporadic compared to familial MEN1 patients." (PMID 29036195, 2017).